RNU6-702P (RNA, U6 small nuclear 702, pseudogene)
Gene: Small nuclear RNA gene on chromosome 18 (22,180,112 to 22,180,218, reverse strand). Ensembl gene ENSG00000201852.
Homologues: Orthologues: chimpanzee U6 (99% identical), macaque U6 (84% identical), dog U6 (82% identical), guinea pig U6 (81% identical), pig U6 (79% identical), rabbit U6 (61% identical). Paralogues in human: RNU6-11P (91% identical), RNU6-37P (91% identical), RNU6-222P (90% identical), RNU6-29P (90% identical), RNU6-33P (90% identical), RNU6-1 (89% identical), RNU6-116P (89% identical), RNU6-2 (89% identical), RNU6-28P (89% identical), RNU6-34P (89% identical), RNU6-39P (89% identical), RNU6-3P (89% identical), and 1287 more.